ATF2 (activating transcription factor 2)
Description:
Transcriptional activator which regulates the transcription of various genes, including those involved in anti-apoptosis, cell growth, and DNA damage response. Dependent on its binding partner, binds to CRE (cAMP response element) consensus sequences (5'-TGACGTCA-3') or to AP-1 (activator protein 1) consensus sequences (5'-TGACTCA-3'). In the nucleus, contributes to global transcription and the DNA damage response, in addition to specific transcriptional activities that are related to cell development, proliferation and death. In the cytoplasm, interacts with and perturbs HK1- and VDAC1-containing complexes at the mitochondrial outer membrane, thereby impairing mitochondrial membrane potential, inducing mitochondrial leakage and promoting cell death. The phosphorylated form (mediated by ATM) plays a role in the DNA damage response and is involved in the ionizing radiation (IR)-induced S phase checkpoint control and in the recruitment of the MRN complex into the IR-induced foci (IRIF). Exhibits histone acetyltransferase (HAT) activity which specifically acetylates histones H2B and H4 in vitro. In concert with CUL3 and RBX1, promotes the degradation of KAT5 thereby attenuating its ability to acetylate and activate ATM. Can elicit oncogenic or tumor suppressor activities depending on the tissue or cell type.
Synonyms: CREB-2; CREB2; TREB7; CRE-BP1; HB16
Tractability: Small molecule: a structure with a bound ligand is known. PROTAC: ubiquitination databases record sites on it; its protein half-life has been measured.
Target class: Transcription factor
Gene: Protein-coding gene on chromosome 2 (175,072,250 to 175,168,382, reverse strand). Ensembl gene ENSG00000115966.
Subcellular location: Nucleus; Cytoplasm; Mitochondrion outer membrane
Subcellular location (Human Protein Atlas): Nucleoplasm
Pathways (Reactome):
Signal Transduction: Estrogen-dependent gene expression; NGF-stimulated transcription; Regulation of PTEN gene transcription
Cellular responses to stimuli: Heme signaling; Response of EIF2AK4 (GCN2) to amino acid deficiency
Chromatin organization: HATs acetylate histones
Circadian clock: Expression of BMAL (ARNTL), CLOCK, and NPAS2
Immune System: Activation of the AP-1 family of transcription factors
Organelle biogenesis and maintenance: Transcriptional activation of mitochondrial biogenesis
Gene Ontology:
Molecular function: cAMP response element binding; cAMP response element binding protein binding; cis-regulatory region sequence-specific DNA binding; DNA-binding transcription activator activity, RNA polymerase II-specific; DNA-binding transcription factor activity; DNA-binding transcription factor activity, RNA polymerase II-specific; histone H2B acetyltransferase activity; histone H4 acetyltransferase activity; identical protein binding; promoter-specific chromatin binding; protein binding; protein kinase binding; RNA polymerase II cis-regulatory region sequence-specific DNA binding; RNA polymerase II transcription regulatory region sequence-specific DNA binding; RNA polymerase II-specific DNA-binding transcription factor binding; sequence-specific double-stranded DNA binding; histone acetyltransferase activity; chromatin binding; DNA binding; leucine zipper domain binding; protein heterodimerization activity; protein homodimerization activity; sequence-specific DNA binding
Biological process: cellular response to leucine starvation; DNA damage response; mitotic intra-S DNA damage checkpoint signaling; negative regulation of angiogenesis; negative regulation of transcription by RNA polymerase II; peptidyl-threonine phosphorylation; positive regulation of cardiac muscle myoblast proliferation; positive regulation of gene expression; positive regulation of mitochondrial membrane permeability involved in apoptotic process; positive regulation of transcription by RNA polymerase II; regulation of DNA-templated transcription; regulation of transcription by RNA polymerase II; response to osmotic stress; transcription initiation-coupled chromatin remodeling; intracellular glucose homeostasis; abducens nucleus development; apoptotic process; BMP signaling pathway; brainstem development; cellular response to anisomycin; cellular response to oxidative stress; cellular response to virus; detection of cell density; facial nucleus development; gene expression; and 20 more
Cellular component: chromatin; cytoplasm; H4 histone acetyltransferase complex; mitochondrial outer membrane; nucleoplasm; nucleus; RNA polymerase II transcription regulator complex; site of double-strand break; membrane
Genetic constraint (gnomAD): Loss-of-function variants: 19 observed, 51.72 expected, observed/expected ratio (o/e) 0.37, 90% interval 0.25 to 0.54. The upper end of that interval is the gene's LOEUF score, 0.54, which puts it in group 2 of 6, group 1 being the genes least tolerant of losing a copy. Missense variants: 410 observed, 586.28 expected, observed/expected ratio (o/e) 0.7, 90% interval 0.64 to 0.76. Synonymous variants: 195 observed, 208.55 expected, observed/expected ratio (o/e) 0.94, 90% interval 0.83 to 1.05.
Homologues: Orthologues: chimpanzee ATF2 (100% identical), macaque ATF2 (100% identical), dog ATF2 (99% identical), pig ATF2 (99% identical), guinea pig ATF2 (99% identical), mouse Atf2 (96% identical), rat Atf2 (95% identical), rabbit ATF2 (93% identical), tropical clawed frog chn1 (73% identical), zebrafish atf2 (71% identical), Caenorhabditis elegans atf-7 (19% identical). Paralogues in human: ATF7 (56% identical), CREB5 (42% identical).
Diseases named in the same sentence as ATF2 in open-access papers:
ATF2 is named in the same sentence as 161 diseases in open-access papers, as found by Europe PMC text mining. Sharing a sentence is not in itself a finding about the gene and the disease. The quoted sentences say what the papers report.
melanoma (46 papers, 2008 to 2025). A malignant, usually aggressive tumor composed of atypical, neoplastic melanocytes. "Last, ATF2, the associated mRNA of ATF2 lncRNA, has been implicated in the progression and therapeutic resistance of many solid cancers, including melanoma, breast cancer, hepatocellular carcinoma, lung cancer, and prostate cancer." (PMID 36831395, 2023). "Primary melanoma specimens that exhibit a high nuclear ATF2:MITF ratio were found to be associated with metastatic disease and poor prognosis." (PMID 24743024, 2014). "A previous study of more than 500 melanoma patients has revealed that strong cytoplasmic ATF2 expression is associated with primary specimens and better survival, whereas strong nuclear ATF2 expression is associated with metastatic specimens and poor survival." (PMID 23878598, 2013). "To assess the mechanism underlying ATF2's contribution to melanoma development, we conducted gene profiling array analysis of primary melanocytes prepared from Tyr::Cre+::Atf2+/+::NrasQ61K::Ink4a−/− and Tyr::Cre+::Atf2md::NrasQ61K::Ink4a−/− mice." (PMID 21203491, 2010). "Significantly, a high nuclear ATF2/MITF ratio in primary melanoma specimens was associated with decreased 10-year disease-specific survival (P = 0.0014)." (PMID 21203491, 2010). "On melanoma tissue microarrays, a high nuclear ATF2 to MITF ratio in primary specimens was associated with metastatic disease and poor prognosis." (PMID 21203491, 2010). "We demonstrate that loss of a transcriptionally active form of ATF2 in melanocytes inhibits melanoma development in an Nras/Ink4a model." (PMID 21203491, 2010). "The significance of these findings is underscored by our observation of human melanoma tumors, in which high ratio of nuclear ATF2 to MITF expression was associated with poor prognosis." (PMID 21203491, 2010). "Nuclear localization of ATF2 in melanoma tumor cells is associated with poor prognosis, likely due to transcriptional activity of constitutively active ATF2." (PMID 21203491, 2010). "The transcription factor ATF2 has been shown to attenuate melanoma susceptibility to apoptosis and to promote its ability to form tumors in xenograft models." (PMID 21203491, 2010). "Active ATF-2 has been linked to the resistance of melanoma cells to chemo- and radiotherapeutic drugs." (PMID 18269766, 2008). "ATF-2 has been implicated in modulating melanoma proliferation and resistance to chemo- and radiotherapy." (PMID 18269766, 2008). "In addition, the p38/ATF2/PI3K/AKT pathway has been implicated in melanoma progression and therapeutic resistance." (PMID 40558540, 2025). "Hence, further studies are required to address mechanisms underlying ATF2 regulation of these pigmentation genes and the significance of such regulation to melanocyte transformation and melanoma development." (PMID 21203491, 2010). "Because active ATF-2 has been implicated in melanoma resistance to chemotherapy, we determined whether RA inhibition of ATF-2 phosphorylation might sensitize B16 cells to the chemotherapeutic agent taxol." (PMID 18269766, 2008). "Thus it is reported that an alternate spliced variant of ATF2 can drive melanomas." (PMID 30120868, 2018). "have found evidence that demonstrates the control of migratory and invasive behaviors of melanoma by ATF2." (PMID 37955015, 2023). "Study confirmed PKCε phosphorylates ATF2 at Thr52, which stimulates ATF2 nuclear localization, leading to a poorer survival prognosis of melanoma patients." (PMID 35641966, 2022). "Increased expression (by inhibition of ATF2 via RNA interference) leads melanoma to undergo cell apoptosis and inhibits growth and metastasis." (PMID 36476606, 2022). "Activated PKCε and ATF2 were observed in advanced-stage melanomas and correlated with decreased cellular protein fucosylation, attenuated cell adhesion, and increased cell motility." (PMID 36358843, 2022).
melanoma (continued). "PKCε-mediated activation of activating transcription factor-2 (ATF2) regulates the migration and invasion of melanoma cells via cellular protein fucosylation." (PMID 36358843, 2022). "Our data is similar to a number of studies mainly in melanoma, pancreatic and oesophageal cancer where inhibition or silencing of ATF2 leads to an induction of apoptosis and inhibition of tumour growth and metastasis." (PMID 33198803, 2020). "ATF2 was involved in suppressing human non‐small cell lung cancer and had effect on melanoma metastasis." (PMID 32476275, 2020). "It has been shown that activating transcription factor 2 (ATF2), associated with cell death or cellular stress states in several melanoma and tumor cell lines, involves Bim and VDAC1, where VDAC1 depletion significantly prevented ATF2-related apoptosis." (PMID 33114780, 2020). "In fact, ATF2 overexpression was necessary for tumor growth and progression in murine skin and for melanoma metastasis in human skin." (PMID 31892232, 2019). "For example, ATF-2 can be an oncogene in one context (e.g. melanoma) and a tumor suppressor in another (e.g. breast cancer)." (PMID 29988723, 2018). "The epsilon isoform of protein kinase C (PKCε) has recently been identified as a master switch that controls the nucleocytoplasmic trafficking of ATF2 and the survival of melanoma cells." (PMID 30497386, 2018). "Overexpression of cytoplasmic ATF2 induced cell death in melanoma, thereby reducing the transcriptional activity of endogenous ATF2." (PMID 27941998, 2016). "By contrast, inhibition of ATF2 repressed tumorigenesis of melanoma via increasing JNK/Jun and JunD activities." (PMID 27377902, 2016). "The nuclear localization of ATF2 coincides with poor prognosis in melanoma patients, and the forced expression of cytoplasmic ATF2 peptides induces apoptosis of melanoma cells." (PMID 26462148, 2015). "In accordance with previous results, genotoxic stress in melanoma cells was found to induce the predominant mitochondrial localization of ATF2 and promote cell death." (PMID 25852302, 2015). "We first examined ATF2 localization and performed apoptosis induction assays in a panel of melanoma cell lines, including B16F10, K1735M2, A375 and A375-R1 cells." (PMID 26462148, 2015). "The mitochondrial accumulation of ATF2 is involved in tumor suppressor activities via cytochrome c release in melanoma cells." (PMID 26462148, 2015). "The mean tumor volume of the B16F10-shATF2 group was significantly larger than the corresponding B16F10 groups (P < 0.05, One way ANOVA), whereas increased mitochondrial ATF2 is observed to block melanoma progression." (PMID 25852302, 2015). "Forced expression of ATF2 increased UVC-induced cell death in melanoma cells while the addition of exogenous TNFα restored cell survival." (PMID 23965971, 2013). "For instance, ATF2 (activating transcription factor 2) a basic transcription factor has been reported to be a regulator of radiation and drug resistance in melanomas and known to induce epithelial–mesenchymal transition (EMT) in pancreatic cancer cell lines." (PMID 24403257, 2013). "In agreement with our findings, Z. Ronai and collaborators have demonstrated the ability of a 51-residue polypeptide derived from the ATF2 transactivating domain (ATF250–100) to alter melanoma growth and metastasis capacity in vivo." (PMID 21858082, 2011). "Surprisingly, the six melanoma lines fell into two classes based on distinct patterns of regulation of MITF by ATF2." (PMID 21203491, 2010). "In all, these findings provide genetic evidence for the role of ATF2 in melanoma development and indicate an ATF2 function in fine-tuning MITF expression, which is central to understanding MITF control at the early phases of melanocyte transformation." (PMID 21203491, 2010). "Significantly, the appearance of nuclear ATF2 is correlated with poor prognosis in melanoma, whereas melanomas that exhibit cytosolic ATF2 exhibit a better survival." (PMID 21203491, 2010).
melanoma (continued). "Given that ATF2 affects activity of the oncogenes N-Ras (mouse model) and BRAF (melanocyte growth on soft agar); we expect that ATF2 play significant roles in melanomas that carry either of these mutations." (PMID 21203491, 2010). "Our findings establish the importance of transcriptionally active ATF2 in melanoma development through fine-tuning of MITF expression." (PMID 21203491, 2010). "As seen in earlier analysis, inhibition of ATF2 expression caused increase in MITF transcription in the human melanocytes and 4 melanoma cell lines, (WM1361, WM793, LU1205, WM35)." (PMID 21203491, 2010). "We demonstrate that melanoma development is markedly attenuated in mice expressing a transcriptionally inactive form of ATF2 in melanocytes." (PMID 21203491, 2010). "This analysis identified 55–63% of tumors as melanomas in both the Atf2+/+ (7/11) and Atf2+/− (10/18) groups." (PMID 21203491, 2010). "Of interest, assessing the localization of ATF2 in the melanoma cell lines studied here revealed that all express nuclear ATF2." (PMID 21203491, 2010). "In all, in about 50% of the melanoma cell lines ATF2 elicits negative regulation of MITF, similar to what was seen in human and mouse melanocytes." (PMID 21203491, 2010). "In agreement, our earlier studies using both human and mouse melanoma lines demonstrate that inhibition of ATF2 effectively inhibits tumorigenesis and blocks metastasis." (PMID 21203491, 2010). "Overall, using the mutant Nras/Ink4a melanoma model we provide genetic evidence for a central role for ATF2 in melanoma development." (PMID 21203491, 2010). "To directly assess the importance of ATF2 in melanoma development, we employed a mouse melanoma model in which ATF2 is selectively inactivated in melanocytes." (PMID 21203491, 2010). "Initially, we assessed changes in MITF expression in six human melanoma lines harboring oncogenic mutations in BRAF or NRAS, and in which ATF2 expression was effectively inhibited by corresponding shRNA (shATF2)." (PMID 21203491, 2010). "Overall, our cohort of 18 melanoma lines revealed that about 50% of the melanomas retained negative regulation of MITF by ATF2, as seen in the melanocytes (primary and cell lines)." (PMID 21203491, 2010). "Significantly, the development of melanoma in mice carrying genetic changes seen in human tumors was inhibited upon inactivation of ATF2 in melanocytes." (PMID 21203491, 2010). "MITF downregulation by ATF2 was confirmed in the skin of Atf2−/− mice, in primary human melanocytes, and in 50% of human melanoma cell lines." (PMID 21203491, 2010). "In contrast to 7/21 of the NrasQ61K::Ink4a−/− mice, only 1/21 mice expressing mutant ATF2 in melanocytes developed melanoma." (PMID 21203491, 2010). "To directly assess ATF2's role in melanoma development, we crossed a mouse melanoma model (NrasQ61K::Ink4a−/−) with mice expressing a transcriptionally inactive form of ATF2 in melanocytes." (PMID 21203491, 2010). "Retinoic acid treatment of B16 melanoma cells decreased ATF-2 phosphorylation likely due to the ability of RA to inhibit the phosphorylation (activation) of p38 MAPK." (PMID 18269766, 2008). "In support of our findings, Ivanov and Ronai reported that treatment of human melanoma cells, already expressing a peptide inhibitor of ATF-2, with a chemical inhibitor of p38 catalytic activity, resulted in apoptosis." (PMID 18269766, 2008). "In the course of determining how retinoic acid (RA) stimulates activating protein-1 (AP-1) activity in B16 melanoma, we discovered that this retinoid decreased the phosphorylation of ATF-2." (PMID 18269766, 2008). "On the basis of these reports, we evaluated the ability of RA, which inhibits ATF-2 phosphorylation (activation), to alter the sensitivity of B16 melanoma cells to taxol-mediated growth suppression." (PMID 18269766, 2008). "ATF-2 and its activating protein kinase, p38, have been found to play an important role in the resistance of melanoma to radiation and chemotherapy." (PMID 18269766, 2008).